CBX2 (chromobox 2)
Diseases named in the same sentence as CBX2 in open-access papers (continued):
Sharing a sentence is not in itself a finding about the gene and the disease.
tumor (50 papers, 2014 to 2025). "Upon initial analysis, we discovered that CBX2 expression identifies a unique tumor cell type and its expression is closely associated with “Epithelial State 6”." (PMID 38984891, 2024). "In prostate cancer, the PRC1 was linked to elevated CCL2-mediated tumor-promoting macrophage recruitment, which supports a potential role of CBX2 in TIME modulation." (PMID 38984891, 2024). "Previous studies revealed that elevated expression of CBX2 was associated with unfavorable survival through retaining CSCs in an undifferentiated state and inhibiting tumor suppressors." (PMID 38702698, 2024). "In BCa, CBX2 is elevated in aggressive tumours with a poor prognosis, and high CBX2 expression is associated with reduced overall survival." (PMID 35884550, 2022). "Future experimental studies are required to address how DNA methylation within the CBX2 locus is associated with oncogenic processes such as cell division within both bulk tumour tissue as well as single tumour cells." (PMID 30820027, 2019). "CBX2 expression was associated with clinical features, including positive lymph node metastasis status, large tumor size and HER-2 positive status." (PMID 29190923, 2017). "This was consistent with the report by Chen and colleagues that protein expression of CBX2 was significantly higher in tumor tissues than adjacent normal tissues, and similarly, CBX2 was found to be significantly associated with positive HER-2 status." (PMID 29190923, 2017). "Interestingly, elevated CBX2 expression is significantly associated with key clinical features, such as positive lymph node metastasis, increased tumor size, and HER-2 positivity." (PMID 40175347, 2025). "Additionally, CBX2 provided prognostic information in the pRCC population, as it was associated with tumor stage and worse clinical outcomes." (PMID 36292141, 2022). "The expression of CBX2 was strongly associated with tumor stage." (PMID 33082469, 2020). "Notably we observed that high expression of CBX2 correlated to a loss of an active tumor suppressor, FOXO3." (PMID 30478317, 2018). "The tumor diagnostic model was formulated as follows: logit (P-HCC) = -2.534 – 1.240 * SOCS2 expression level - 1.320 * LCAT expression level + 0.335 * FTCD expression level – 1.911 * KRT17 expression level + 4.422 * PBK expression level + 2.006 * CBX2 expression level." (PMID 36159831, 2022). "The tumor diagnostic model was formulated as follows: logit (P-HCC) = 6.906 - 0.494 * SOCS2 expression level - 1.250 * LCAT expression level – 0.493 * FTCD expression level + 0.602 * KRT17 expression level + 1.950 * PBK expression level + 7.243 * CBX2 expression level." (PMID 36159831, 2022). "Moreover, examination of five patients with matched primary tumor, ascites-associated tumor cells, and distant metastasis revealed three of the five patients had an increase in CBX2 expression in distant metastasis/ascites-associated tumor cells compared to primary tumors." (PMID 30478317, 2018). "Conversely, CBX2 knockdown inhibits tumor growth and sensitizes cells to chemotherapy by restoring PTEN activity and suppressing the AKT/mTOR pathway." (PMID 40565099, 2025). "Dysregulation of CBX2 can disrupt essential epigenetic controls, contributing to tumor initiation and progression by affecting cell proliferation and survival pathways." (PMID 40175347, 2025). "The HeLa CBX2-OE tumors exhibited a higher tumor volume trend and a higher tumor weight compared to the CBX2-vector tumors." (PMID 39793896, 2025). "We sought to explore the impact of modulation of CBX2 on the tumor immune microenvironment (TIME), understanding that the TIME plays a critical role in disease progression and development of therapy resistance." (PMID 38984891, 2024).
tumor (continued). "Xenograft tumours were generated in nude mice by injecting CBX2 deletion HCT116 and control cells subcutaneously and examined tumour growth." (PMID 38495501, 2024). "Although we predict that CBX2-mediated regulation of TAM differentiation and activity is highly complex, our findings suggest a unique CBX2/CXCL1 or CBX2/CXCL8 axis in tumor cells that aid in remodeling the HGSC TIME." (PMID 38984891, 2024). "NanoString transcriptomic analysis was performed on the tumor specimens, comparing shCbx2 with intact Cbx2 and 162 differentially expressed genes were found." (PMID 38984891, 2024). "State 6 is defined by increased expression of CBX2 and accounts for 30% of all tumor cells in HGSC tumors, thus contributing to one of the largest proportions of cells." (PMID 38984891, 2024). "As expected, deletion of CBX2 significantly hampered cell proliferation and tumour progression in vitro and in vivo." (PMID 38495501, 2024). "Relative to shCTRL, the number of dissemination sites and total tumor weight were significantly reduced in the Cbx2 knockdown tumor-bearing mice, and tumor weight was measured with a similar significant decrease in both knockdown lines." (PMID 38984891, 2024). "We found that deletion of CBX2 markedly suppressed tumour growth and reduced tumour size, volume, and weight in comparison with the control group." (PMID 38495501, 2024). "In the LinkedOmics database, CBX2, NOTCH3, HDAC6 and HDAC11 were linked with tumor purity and TNM stage." (PMID 38702698, 2024). "Knockdown of CBX2 leads to a significant reduction in tumor cell proliferation and promotes anoikis, which increases the sensitivity of tumor cells to pods." (PMID 38355480, 2024). "In this series of investigations, we observed that an understudied epigenetic reader protein, CBX2, promotes the transcriptional reprogramming of tumor cells to support the differentiation of TAMs." (PMID 38984891, 2024). "The clinicopathological analysis showed that the expression level of CBX2 was significantly correlated with tumour size (p < 0.001), histological grade (p < 0.001) and postoperative recurrence (p < 0.021)." (PMID 39114365, 2024). "Compared with patients with a low level of CBX2, patients with a high level of CBX2 had a larger tumour size (≥40 mm), higher histological grade (grade III-IV) and higher risk of postoperative recurrence." (PMID 39114365, 2024). "A total of 842 malignant cells from GSE125449 and 4500 malignant cells from GSE166635 were used to validate the influence of CBX2 on tumor stemness using CytoTRACE." (PMID 37980163, 2023). "In glioma, CBX2 inhibits tumor growth; whereas in lung, liver, and colon cancers it promotes tumorigenesis." (PMID 38030604, 2023). "Specifically, the median expression of CBX2 showed an evident increase with more advanced tumor stages in pRCC, while the median expression of CBX7 showed decreasing trends in both RCC subtypes." (PMID 36292141, 2022). "For example, CBX2 and CBX7 have been shown to have contrasting roles in BCa metabolism and cell growth, with CBX2 being associated with aggressive tumour subtypes and poorer patient outcomes." (PMID 35884550, 2022). "MRNA expressions of CBX1, CBX2, CBX3, CBX4, and CBX8 were significantly associated with tumor grades." (PMID 35464847, 2022). "Statistically, the mRNA expression of CBX2/3/8 tended to be higher as tumor grade increased, whereas the mRNA expression of CBX6/7 tended to be lower with increasing tumor grade." (PMID 35210369, 2022). "The upregulated expression of CBX2/3/8 was found to be both correlated with the tumor grade and recurrent status." (PMID 35210369, 2022). "Otherwise, in the pRCC subtype, CBX2, CBX3, CBX7, and CBX8 were deregulated, and CBX2, CBX6, and CBX7 were associated with the tumor stage." (PMID 36292141, 2022). "The results exhibited that the mRNA expression of CBX2/3/8 tended to be higher as tumor grade increased, whereas the mRNA expression of CBX6/7 tended to be lower with increasing tumor grade." (PMID 35210369, 2022).
tumor (continued). "Overall, transcripto‐metabolomic data of tumor samples along with experimental data conclusively demonstrate the role of CBX2/7 in glycolytic regulation." (PMID 33400401, 2021). "Of note, significantly statistical differences between tumor stages I–IV were only identified in the CBX2 group (P = 0.021)." (PMID 34321009, 2021). "The results showed that when compared with normal tissues, the mRNA expression level of CBX7 was downregulated in tumor tissues with different stage, whereas CBX2/3/4/8 was upregulated." (PMID 34117289, 2021). "In agreement with patient tumor data, silencing of CBX2 and CBX7 showed opposite effects on all six measured end‐points." (PMID 33400401, 2021). "Regarding PAAD, increased CDCA expression along with advanced PAAD tumor stage, NUF2, CDCA2, CDCA3, CDCA4 and CDCA5 expression are risk factors for poor prognosis, while CBX2 expression is a protective factor (P < 0.05)." (PMID 33437202, 2021). "CBX2 overexpression can promote tumor proliferation, while the overexpression of miR-8485 can inhibit the expression of CBX2." (PMID 35008817, 2021). "Similar results were also obtained for CBX2 (tumor specimens: 6.85 ± 0.38; normal ovarian tissues: 1.15 ± 0.20, P < 0.01) and CBX3 (tumor specimens: 8.65 ± 0.31; normal ovarian tissues: 0.54 ± 0.12, P < 0.01) protein expression." (PMID 32742466, 2020). "Pathways that were overrepresented in tumours that overexpress CBX2 include cell cycle checkpoint regulation." (PMID 30820027, 2019). "Accumulating evidence indicates that CBX2 is overexpressed in multiple human neoplasm and play a critical role in tumorigenesis and progression." (PMID 31150156, 2019). "Second, tumours that overexpress CBX2 are mostly classified as HER2+ or basal-like, an aggressive subtype against which there are no specific chemotherapeutic interventions and are associated with poor overall 5-year survival." (PMID 30820027, 2019). "In tumor cells, Cbx2 is up-regulated and has been identified as a potential drug target, whereas our results demonstrate that Cbx2 is down-regulated in macrophages infected with virus." (PMID 30357595, 2019). "Consistently, the average tumor luciferase activity and tumor weight were significantly decreased after CBX2 knockdown." (PMID 31150156, 2019). "CBX2 expression level was positively associated with the expression of PCNA and Ki67, two proliferation markers of neoplasm." (PMID 31150156, 2019). "The survival analysis was applied to all 1084 cases, instead of the 110 cases with tumour-adjacent normal pairs, because we wanted to evaluate the clinical impact of CBX2 more broadly in the patient population." (PMID 30820027, 2019). "In summary, we have identified an OC, CBX2, based on a model that captures subgroups of tumours that overexpress mRNA relative to normal tissue." (PMID 30820027, 2019). "Taken together, these data demonstrate that CBX2 upregulation in HGSOC is associated with poorer prognosis, repression of the FOXO3 tumor suppressor, and is possibly linked to chemoresistance." (PMID 30478317, 2018). "In a primary human HGSOC tumor microarray we observed high CBX2 expression in a majority of specimens." (PMID 30478317, 2018). "The highest mRNA expressions of CBX1/3/4/5/6/8 were found in tumor grade 4, while the highest mRNA expression of CBX2 was found in grade 3." (PMID 30481161, 2018). "Utilizing densitometry, CBX2 expression was observed to be significantly higher in HGSOC primary tumor compared to FTE or benign tissues (Rank-sum test p value 0.0333)." (PMID 30478317, 2018). "Given the up-regulation of CBX2 in both CRPC and NEPC, we posit that CBX2 is required for tumor cell survival following castration but that other molecular mechanisms define specialization into neuroendocrine or epithelial lineages." (PMID 26877821, 2016).
tumor (continued). "To confirm the results obtained in the 313B/BR model, we assessed the expression of CBX2 in a panel of PCa PDX models that were either androgen-dependent (n = 10) or androgen-independent (n = 5) available at the Living Tumor Laboratory." (PMID 26877821, 2016). "In line with the idea that CBX2 promotes tumor progression, the biological processes and functions associated with CRGs were intricately related with proliferation." (PMID 26877821, 2016). "Based on this model, our results suggest that a small population of CBX2-expressing PCa cells within the primary tumor is the likely seed of metastatic dissemination." (PMID 26877821, 2016). "We have shown that high CBX2 expression correlates with poor patient outcome and more aggressive tumor phenotypes, in line with the clinical features of NEPC." (PMID 25859291, 2015). "In vitro studies have shown that CBX2 can promote tumor growth and invasiveness by activating the PI3K/AKT pathway, a signaling cascade inducing phosphatidylinositol 3-kinase (PI3K), which phosphorylates phosphatidylinositol 4,5-bisphosphate (PIP2) to generate PIP3." (PMID 40175347, 2025). "CBX2-KD HeLa and SiHa cell formed fewer tumor spheres compared to HeLa NC and SiHa NC cells." (PMID 39793896, 2025). "What’s more, mounting evidences suggested that CBX2 could block differentiation and promote self-renewal of CSCs, thus playing an important part in tumor initiation and development." (PMID 38702698, 2024). "Notably, our study found that DLBCL cells with CBX1 over-expression were resistant to the common anti-tumor drugs, but CBX2/5 had two polarities." (PMID 37430195, 2023). "Three scRNA-seq datasets GSE125449, GSE140228 and GSE166635 downloaded from the TISCH2 database were analyzed, and we found that CBX2 was primarily expressed in cancerous tumor cells while CEP55 was primarily expressed in T cells that were proliferating (T prolif), whose marker gene MKI67." (PMID 37980163, 2023). "In aggregate, CBX2 functions as a tumor accelerator in BC through multiple pathways." (PMID 38030604, 2023). "CBX2 functions as a potent tumor accelerator in BC, promoting tumorigenesis through multiple pathways including the PI3K/AKT signaling pathway, metabolic reprogramming, and intronic DNA methylation, which possibly mainly attribute to regulation of gene expression at chromatin." (PMID 38030604, 2023). "In addition, the upregulated expression of CBX2/3/8 and downregulation of CBX6/7 were discovered to be associated with the tumor grade." (PMID 35210369, 2022). "Inhibition of CBX2 may therefore prevent tumour growth via re-activation of DREAM complex-mediated cell senescence." (PMID 35884550, 2022). "The increase of CBX2/3/4/5 and a decrease of CBX7 in comparison to adjacent tissues in GC may be caused by the potential differences in cellular content in tumor vs. adjacent tissues." (PMID 34117289, 2021). "Moreover, CBX2/7 protein correlated in opposite directions with phosphorylation of ribosomal S6 protein at serine 235/236 and serine 240/244 in TCGA tumor samples, further implying the role of mTORC1 signaling." (PMID 33400401, 2021). "In addition, CBX2 and ki‐67 were assessed using IHC analysis in xenograft tumor tissues and results revealed that both CBX2 and Ki‐67 staining intensities were markedly decreased in the tumors from the sh‐CBX2 group." (PMID 31150156, 2019). "First, CBX2 is expressed at low levels in most healthy adult female tissues and targeted CBX2 inhibition may therefore spare non-tumour tissue and result in fewer side effects." (PMID 30820027, 2019). "To validate these results, we assessed CBX2 expression in both tumor lines using quantitative reverse transcription polymerase chain reaction (qRT-PCR), which confirmed that CBX2 expression was 3.2-fold higher in LTL313H compared to LTL313B (p < 0.0001, Student’s t test)." (PMID 26877821, 2016).
tumor (continued). "Furthermore, there was a clear inverse relationship between CBX7 and CBX8 (and to a minor extent CBX2) mRNA expression levels of tumor and normal samples in the TCGA tumor data set overexpressing miR-375." (PMID 27449098, 2016). "Given the pro-survival properties conferred by CBX2 in vitro, we posit that CBX2 up-regulation may serve as an adaptive mechanism to bypass the anti-tumor response elicited by castration." (PMID 26877821, 2016). "Notably, ITGB8, DICER1, INPP5A, PIK3R1, and TIMP2 are key tumor suppressors that were among up-regulated CRGs following CBX2 knockdown." (PMID 26877821, 2016). "In addition, SCUBE2 was significantly associated with lymph node status (P = 0.01), CBX2 with tumor inflammatory infiltration (P = 0.03), and STK32B with tumor size (P = 0.04)." (PMID 24885002, 2014). "We found that CBX2, SCUBE2, and STK32B protein expression were associated with important clinicopathological features for OSCC (peritumoral inflammatory infiltration, metastatic spread to the cervical lymph nodes, and tumor size)." (PMID 24885002, 2014). "Thus, we hypothesized that CBX2 enhances the chemoresistance and radioresistance of tumor cells by maintaining stemness of tumor cells." (PMID 39793896, 2025). "Additionally, with the increase of tumour staging, the expression level of CBX2 also increased significantly, suggesting that CBX2 may be related to a low prognosis in patients with CRC." (PMID 38495501, 2024). "The identification of a strong association between DNA methylation—a reversible transcriptional regulatory process—and CBX2 overexpression suggests that CBX2 expression may be reversibly regulated to drive important tumour behaviour, such as the switch between cell division and metastasis." (PMID 30820027, 2019). "Other EpiGs highly induced in tumor tissues, such as HDAC11 and CBX2, are attracting significant attention as chromatin regulators capable of predicting prognosis and therapeutic responses." (PMID 40504449, 2025). "Analysis revealed elevated expression of CBX2/3/5/8 and reduced expression of CBX6/7 in GBM, with correlations to tumor grade and recurrence." (PMID 40565099, 2025). "We observed that CBX2 expression delineates a unique HGSC epithelial cell type and modulating CBX2 in tumor cells leads to a differential immune microenvironment." (PMID 38984891, 2024). "CBX2 is a new potential target in HGSC and other malignancies, with the hope of limiting tumor progression and resensitizing to therapy." (PMID 38984891, 2024). "Taken in the context of our current and prior findings showing CBX2 is critical for HGSC progression, targeting CBX2 in tumor cells provides an opportunity to limit tumor progression and potentially alleviate an immune-suppressed microenvironment." (PMID 38984891, 2024). "The qRT-PCR results revealed a significant upregulation of CBX2, SPP1, and ZC4H2, alongside a notable downregulation of FMO3 in tumor tissues." (PMID 37287752, 2023). "The high expressions of the CBX family (including CBX2, CBX3, CBX5, and CBX6) in tumor tissues were related to the worse OS of DLBCL patients, whereas high expression of CBX1 was correlated with better prognosis of patients." (PMID 37430195, 2023). "Significant disparities in protein expression levels of CBX2, SPP1, ZC4H2, and FMO3 were detected between tumor tissues and matched para-tumor tissues." (PMID 37287752, 2023). "This analysis has therefore identified a mechanism by which the tumour suppressor RBL2 is repressed in TNBC and proposes that CBX2 promotes TNBC cell growth via inhibition of DREAM complex activity." (PMID 35884550, 2022). "The mRNA expression of CBX1, CBX2, CBX3, CBX4, and CBX8 tended to be elevated as the tumor grade increased." (PMID 35464847, 2022).